STX17 (syntaxin 17)
Diseases named in the same sentence as STX17 in open-access papers (continued):
Sharing a sentence is not in itself a finding about the gene and the disease.
ischemia (1 paper, 2024). A hypoperfusion of the BLOOD through an organ or tissue caused by a PATHOLOGIC CONSTRICTION or obstruction of its BLOOD VESSELS, or an absence of BLOOD CIRCULATION. "We first investigated the correlation variations between NSF activity and the expressions of STX17 and VAMP8 after the ischemia." (PMID 39155286, 2024). "The relevant alterations between NSF activity and expressions of STX17 and VAMP8 were investigated after ischemia." (PMID 39155286, 2024).
ischemic stroke (1 paper, 2024). A stroke disorder caused by obstruction of blood flow to the brain, due to thrombotic (local blood clot formation) or embolic (due to a blood clot or other material traveling from another site) event. "The results demonstrated that NSF was prominently inhibited, coupling with decreased expressions of STX17 and VAMP8 in penumbral neurons 48 h after ischemic stroke, as well as in HT22 neurons 2 h after OGD." (PMID 39155286, 2024).
myeloproliferative neoplasm (1 paper, 2025). A clonal hematopoietic stem cell disorder, characterized by proliferation in the bone marrow of one or more of the myeloid (i.e., granulocytic, erythroid, megakaryocytic, and mast cell) lineages. "Using human and murine models of TNF-α–driven diseases, including myeloproliferative neoplasms and rheumatoid arthritis, we found that TNF-α downregulates syntaxin 17 (STX17), a key mediator of autophagosome-lysosome fusion." (PMID 40493419, 2025).
Obesity (1 paper, 2025). Accumulation of substantial excess body fat. "Immunofluorescence for STX17 or SNAP29 co-staining with F4/80 indicated a lower average expression of STX17 or SNAP29 in ATMs of the obesity-related SAP group." (PMID 40806352, 2025). "The immunohistochemistry of adipose tissue showed decreased STX17 and SNAP29 puncta in obesity-related SAP mice." (PMID 40806352, 2025). "Western blot and qPCR analyses demonstrated that both the induction of obesity and SAP reduced the protein or mRNA levels of STX17 and SNAP29 in adipose tissue." (PMID 40806352, 2025). "The results showed that the expression of STX17 and SNAP29 in adipose tissue significantly decreased after the induction of obesity and SAP." (PMID 40806352, 2025).
pancreatitis (1 paper, 2024). Inflammation of the pancreas. "Knockout of SNAP23 impaired the assembly of STX4‐driven basolateral exocytotic SNARE complex and STX17‐driven SNARE complex, resulting in reduction of autophagosome formation, thus protecting pancreatitis progression." (PMID 39500626, 2024).
pulmonary fibrosis (1 paper, 2025). Chronic progressive interstitial lung disorder characterized by the replacement of the lung tissue by connective tissue, leading to progressive dyspnea, respiratory failure, or right heart failure. "Conversely, promoting Hcy catabolism, either through MTRR overexpression or folate administration, reduced STX17 homocysteinylation and ameliorated pulmonary fibrosis." (PMID 40990430, 2025). "Notably, pharmacological folate administration reverses STX17 depletion, restoring autophagic flux and mitigating pulmonary fibrosis in mouse models." (PMID 40990430, 2025). "Importantly, Fol treatment was shown to reduce Hcy levels, inhibit the homocysteinylation of STX17, restore autophagic flux, and ultimately reverse lung fibrosis." (PMID 40990430, 2025).
retinal diseases (1 paper, 2024). "While STX17 does not exclusively mediate autophagosome/lysosome fusion in the retina and RPE, there are emerging connections between STX17 and retinal diseases." (PMID 38799985, 2024).
infection (11 papers, 2016 to 2025). The state of being infected such as from the introduction of a foreign agent such as serum, vaccine, antigenic substance or organism. "Using quantitative real-time RT-PCR, we demonstrate that genes encoding for Atg5, LC3B, hVps34, UVRAG, and STX17 are significantly up-regulated 6 h post-infection." (PMID 27242971, 2016). "Infection with WT Legionella led to the formation of STX17-GFP vesicles; the number of vesicles was significantly lower in cells infected with the ΔS strain, showing PR-Ub was important for the formation of STX17+ vesicles." (PMID 40506485, 2025). "STX17 is a substrate of the Legionella serine protease Lpg1137, and although the levels of STX17 are unaffected by the protease 1 h post-infection, almost complete Lpg1137-dependent degradation has occurred after 4 h." (PMID 40506485, 2025). "We observed STX17+ vesicles and the recruitment of STX17 to bacteria during the first 2 h post-infection." (PMID 40506485, 2025). "In our experiments using Legionella-infected cells, we observed elongated STX17-coated bacterial vacuoles surrounding individual rod-shaped bacteria 2 h post-infection." (PMID 40506485, 2025). "We found that LncRNA-GAS5 was up-regulated following infection with Acinetobacter baumannii, thus resulting in the degradation of STX17, autophagy disorders, and the aggravated replication of Acinetobacter baumannii." (PMID 34304694, 2021). "Having already observed the recruitment of STX17 to bacteria, we sought to determine whether other autophagy markers were also recruited to the bacterial vacuole 2 h post-infection." (PMID 40506485, 2025). "To check whether the maturation and size of LCVs was dependent on STX17, we immunostained LCVs at a late stage of infection (12 h.p.i)." (PMID 40506485, 2025). "Notably, infection of lentiviral GFP-tagged Stx17 into Kansl1fl/+/CAG-cre neurons led to partial restoration of mitophagic activity." (PMID 35177641, 2022). "Our research indicated that the GAS5/YY1/STX17 pathway may represent a new regulatory network that controls the disruption of autophagy in response to infection by Acinetobacter baumannii." (PMID 34304694, 2021). "Proteomic analysis has shown that the SNARE proteins Syntaxin17 (STX17) and SNAP29 are PR-ubiquitinated during infection." (PMID 40506485, 2025). "Upon infection, GPNMB interacts with autophagosomal-localized STX17, leading to a reduced N-glycosylation level at N296 of GPNMB." (PMID 40038549, 2025). "Although ZIKV initially activates autophagy in TM, it impairs the overall autophagic flux during infection by modulating the VPS39, a HOPS complex, and STX17, a SNARE complex protein, to inhibit autophagosomal maturation." (PMID 40920489, 2025). "During infection, GPNMB bound to autophagosomal-localized STX17, leading to the deglycosylation of GPNMB, which promoted SNAP29 degradation." (PMID 40038549, 2025). "We further found that 2BC non-structural protein of EV-A71 specifically interacts with STX17 and SNAP29, and this reaffirms the importance of STX17 and SNAP29 in EV-A71 infection." (PMID 28677644, 2017). "Stx17 was not cleaved on infection with these mutants, as in the case of the dotA mutant." (PMID 28504273, 2017).
tumor (9 papers, 2012 to 2025). "The result strongly suggests that an elevated copy number of the 4.6 kb STX17 sequence is a driver mutation in these tumours." (PMID 38571883, 2024). "Horse melanomas are spontaneous and usually benign tumors, and a 4.6 kb duplication in intron 6 of STX17 (syntaxin-17) causes the tumor phenotype, which constitutes a cis-acting regulatory mutation." (PMID 36052162, 2022). "In GB7225 specimen with high level of autophagy (higher expression of LC3B, STX17 and lower expression of SQSTM1), HMGB1 in the nuclei and cytoplasm of tumor cells was significantly diminished." (PMID 35193644, 2022). "Taken together, SLC7A11 acted as a ceRNA for STX17, UVRAG, and RAB33B in 20, 12, and 12 different tumor types, respectively, and acted as a ceRNA for the three genes in 379 OC tissues and in 90 drug-resistant tissues." (PMID 34790572, 2021). "However, in GB1388 specimen with lower levels of autophagy (lower expression of LC3B, STX17 and higher expression of SQSTM1), HMGB1 accumulated in the nuclei and cytoplasm of tumor cells." (PMID 35193644, 2022). "mRNA from the tumour samples ID1 and ID2 were used for expression analysis in our previous study and both samples had upregulated expression of STX17 and NR4A3 consistent with our interpretation that the copy number expansion detected in the present study may be relevant for tumour development." (PMID 22857264, 2012).
cancer (3 papers, 2019 to 2020). A tumor composed of atypical neoplastic, often pleomorphic cells that invade other tissues. "In normal human fibroblast cells, BAP31 is also associated with STX17, which suggests that BAP31 associates with STX17 in both normal cells and cancer cells." (PMID 31671609, 2019). "All these reports put forward the role of autophagy regulators like Stx17 as a potential new target in cancer therapy." (PMID 32792960, 2020). "Moreover, Stx17 is a key regulator of fusion between autophagosomes and lysosomes, and this step is being targeted in various cancer using chloroquine and hydroxychloroquine." (PMID 32792960, 2020).
bacterial infection (2 papers, 2025). "Moreover, the binding of GPNMB with STX17 was enhanced upon bacterial infection." (PMID 40038549, 2025). "Taken together, our data revealed that GPNMB blocked cellular autophagic flux by disrupting the interaction between STX17 and SNAP29 during bacterial infection." (PMID 40038549, 2025). "Upon bacterial infection, GPNMB is recruited to autophagosomes through interaction with STX17, disrupting the assembly of the STX17-SNAP29-VAMP8 SNARE complex." (PMID 40038549, 2025). "The Stx17–Snap29–Vamp8 complex also plays a crucial role in fish immune responses, with bacterial infection activating the STING pathway, which regulates the assembly of Stx17 with the Snap29–Vamp8 complex, thereby affecting autophagic flux and immune responses." (PMID 40076623, 2025).
neurodegenerative disease (2 papers, 2019 to 2024). A disorder of the central nervous system characterized by gradual and progressive loss of neural tissue and neurologic function. "Delineating the causative factor and sequential consequences of STX17-initiated mitophagy, regulated by Fis1, may lead to greater insights into interventions on diseases, particularly for therapeutics on neurodegenerative diseases." (PMID 31053718, 2019). "Through this comprehensive exploration, we aim to provide valuable insights into the potential therapeutic strategies for neurodegenerative diseases induced by Meth, emphasizing the regulatory significance of Stx17 in the autophagic process." (PMID 38172666, 2024). "Therefore, our work underscores the importance of Stx17 in regulating autophagy and provides insight into potential therapeutic strategies for Meth-induced neurodegenerative diseases." (PMID 38172666, 2024).
infectious disease (1 paper, 2022). A disorder directly resulting from the presence and activity of a microbial, viral, or parasitic agent in humans. "Syntaxin-17 (STX17), a SNARE protein, interacts with CFTR and the loss of the CFTR-STX17 interaction impairs bacterial clearance and could play a critical role in infectious diseases among CF patients." (PMID 35269585, 2022).
STX17 also shares sentences with these, for which no sentence is quoted: vitiligo (5 papers); Alzheimer disease (1); atherosclerosis (1); Autoimmunity (1); breast carcinoma (1); cervical cancer (1); glioblastoma (1); Hyperglycemia (1); inflammation (1); lung carcinoma (1); memory impairment (1); nonalcoholic fatty liver disease (1); preeclampsia (1); rheumatoid arthritis (1).